HSPE1-MOB4 (HSPE1-MOB4 readthrough)
Synonyms: HSPE1-PHOCN
Gene: Protein-coding gene on chromosome 2 (197,500,413 to 197,550,726, forward strand). Ensembl gene ENSG00000270757.
Genetic constraint (gnomAD): Loss-of-function variants: 5 observed, 38.13 expected, observed/expected ratio (o/e) 0.13, 90% interval 0.068 to 0.28. The upper end of that interval is the gene's LOEUF score, 0.28, which puts it in group 1 of 6, group 1 being the genes least tolerant of losing a copy. Missense variants: 159 observed, 311.84 expected, observed/expected ratio (o/e) 0.51, 90% interval 0.45 to 0.58. Synonymous variants: 90 observed, 99.11 expected, observed/expected ratio (o/e) 0.91, 90% interval 0.76 to 1.08.